U8 (U8 small nucleolar RNA )
Synonyms: LOC124900356
Gene: Small nucleolar RNA gene on chromosome 15 (32,426,288 to 32,426,420, reverse strand). Ensembl gene ENSG00000206987.
Gene Ontology:
Biological process: RNA processing
Cellular component: nucleolus
Homologues: Orthologues: chimpanzee U8 (98% identical), rabbit U8 (55% identical). Paralogues in human: U8 (98% identical), U8 (97% identical), U8 (80% identical), U8 (78% identical), U8 (77% identical), U8 (74% identical), U8 (73% identical), U8 (71% identical), U8 (69% identical), U8 (67% identical), U8 (66% identical), U8 (44% identical).